HABP4 (hyaluronan binding protein 4)
Description:
Ribosome-binding protein that promotes ribosome hibernation, a process during which ribosomes are stabilized in an inactive state and preserved from proteasomal degradation (By similarity). Acts via its association with EEF2/eEF2 factor at the A-site of the ribosome, promoting ribosome stabilization in an inactive state compatible with storage (By similarity). Plays a key role in ribosome hibernation in the mature oocyte by promoting ribosome stabilization (By similarity). Ribosomes, which are produced in large quantities during oogenesis, are stored and translationally repressed in the oocyte and early embryo (By similarity). Also binds RNA, regulating transcription and pre-mRNA splicing. Binds (via C-terminus) to poly(U) RNA. Seems to play a role in PML-nuclear bodies formation. Negatively regulates DNA-binding activity of the transcription factor MEF2C in myocardial cells in response to mechanical stress (By similarity).
Synonyms: IHABP-4; IHABP4; SERBP1L; Ki-1/57
Tractability: Antibody: its Gene Ontology location is reachable by antibodies, with high confidence. PROTAC: UniProt records ubiquitination sites on it; its protein half-life has been measured.
Gene: Protein-coding gene on chromosome 9 (96,450,160 to 96,491,336, forward strand). Ensembl gene ENSG00000130956.
Subcellular location: Nucleus; Cytoplasm; Cytoplasm, Stress granule; Cytoplasm, sarcoplasm; Nucleus, nuclear body; Nucleus, nucleolus; Nucleus speckle; Nucleus, Cajal body; Nucleus, gem
Subcellular location (Human Protein Atlas): Nuclear membrane; Cytosol
Pathways (Reactome):
Hemostasis: Platelet degranulation
Gene Ontology:
Molecular function: protein binding; SUMO binding; ribosome binding; translation elongation factor binding; RNA binding
Biological process: PML body organization; positive regulation of RNA splicing; positive regulation of translational initiation; cellular response to mechanical stimulus; ribosome hibernation
Cellular component: Cajal body; cytoplasm; cytoplasmic stress granule; cytosol; Gemini of Cajal bodies; nuclear membrane; nuclear speck; nucleolus; nucleus; extracellular region; sarcomere; nuclear body; sarcoplasm
Genetic constraint (gnomAD): Loss-of-function variants: 11 observed, 10.83 expected, observed/expected ratio (o/e) 1.02, 90% interval 0.64 to 1.65. The synonymous counts are far from expectation, so gnomAD's model fits this gene poorly and the ratio says little. Missense variants: 283 observed, 212.23 expected, observed/expected ratio (o/e) 1.33, 90% interval 1.21 to 1.47. Synonymous variants: 135 observed, 96.43 expected, observed/expected ratio (o/e) 1.4, 90% interval 1.22 to 1.62.
Homologues: Orthologues: chimpanzee HABP4 (99% identical), macaque HABP4 (98% identical), pig HABP4 (90% identical), dog HABP4 (89% identical), mouse Habp4 (86% identical), rat Habp4 (86% identical), guinea pig HABP4 (68% identical), tropical clawed frog habp4 (45% identical), zebrafish zgc:103482 (41% identical), Drosophila melanogaster vig (27% identical), Drosophila melanogaster vig2 (26% identical), Drosophila melanogaster PPYR1 (16% identical). Paralogues in human: SERBP1 (43% identical).
Diseases named in the same sentence as HABP4 in open-access papers:
HABP4 is named in the same sentence as 23 diseases in open-access papers, as found by Europe PMC text mining. Sharing a sentence is not in itself a finding about the gene and the disease. The quoted sentences say what the papers report.
colon cancer (2 papers, 2020 to 2023). "The 9q22.3-3.1 region is in clear linkage disequilibrium with SNP haplotypes in the families with higher colon cancer risk and therefore puts HABP4 as the main candidate gene in the spotlight." (PMID 33245729, 2020). "In an analysis of familial colon cancer risk-associated SNP haplotypes, the human gene encoding the protein intracellular hyaluronic acid-binding protein 4 (HABP4), has been found in linkage disequilibrium." (PMID 33245729, 2020). "Although the detailed underlying molecular mechanisms need to be further characterized in future experiments, HABP4 seems to be an interesting candidate to explore new diagnostic, prognostic and possibly even therapeutic avenues in colon cancer." (PMID 33245729, 2020). "We established the relevance of HABP4 for colon cancer development by demonstrating the increased number of tumors in a mouse model for colitis-associated colon cancer in Habp4–/–, which is convergent with the down regulation of HABP4 expression in patients with colorectal cancer." (PMID 33245729, 2020). "In summary, our new data from the HABP4 mouse and human cell culture knockout models, together with expression data from colon cancer patient samples and literature data, suggest that HABP4 is a new tumor suppressor candidate." (PMID 33245729, 2020). "Our study of the protein expression levels of HABP4 in human colon cancer samples, through immunohistochemistry assays, showed, that 30% of the tumors analyzed had low expression of HABP4." (PMID 33245729, 2020). "Since the gene of HABP4 is located in a region of the chromosome 9 that has linkage related to familiar colon cancer and leukemia, we decided to explore this possible connection further." (PMID 33245729, 2020). "A Habp4–/– knockout mice and colon cancer cell lines were generated using the CRISPR/Cas9 gene-editing system." (PMID 33245729, 2020). "Our data suggest that HABP4 is involved in proliferation regulation of colon cells in vitro and in vivo and that it is a promising new candidate for a tumor suppressor protein that can be explored both in the diagnosis and possibly therapy of colon cancer." (PMID 33245729, 2020). "In this study, we addressed the impact of HABP4 gene deletion, on the development of colon cancer." (PMID 33245729, 2020). "The experiments reported in this article suggest that HABP4 may represent a novel tumor suppressor in colon cancer." (PMID 33245729, 2020). "Based on these findings we generated the knockout mice for the gene of HABP4 and employed an inducible colon cancer model (AOM/DSS) in the normal and knockout mice littermates to test if there are differences in the cell proliferation and other cancer related features." (PMID 33245729, 2020). "A later study in a familial form of colon cancer also was able to zoom in to a region around 9q22.2-31.2, in which aside the gene of HABP4 only three other genes are found, which seem to be less likely candidates for oncoproteins or tumor suppressors (ZNF367, GABBR2 and GALNT12)." (PMID 33245729, 2020). "Altogether, these data suggest that HABP4 may be involved in colon cancer." (PMID 33245729, 2020). "To test a possible role of HABP4 in tumorigenesis we generated knockout mice by the CRISPR/Cas9 method and treated the animals with azoxymethane (AOM)/dextran sodium sulfate (DSS) for induction of colon tumors." (PMID 33245729, 2020).
acute myeloid leukemia (1 paper, 2020). Acute myeloid leukemia (AML) is a group of neoplasms arising from precursor cells committed to the myeloid cell-line differentiation. "The first concrete link that suggested some relevance of HABP4 in cancer was soon after it ́s cloning, when FISH experiments showed that the gene of HABP4 is located in region 9q22.3-3.1 of the chromosome 9 that had been reported as a hot spot for secondary aberrations in acute myeloid leukemia." (PMID 33245729, 2020).
glioblastoma (1 paper, 2020). The most malignant astrocytic tumor (WHO grade IV). "Although many functional features tend to overlap between HABP4 and SERBP1, in relation to cancer the data so far point in opposite directions, since SERBP1 has been reported to be over-expressed in several cancer settings, including ovary, breast, colon, prostate, glioblastoma and lung cancer." (PMID 33245729, 2020).
Hodgkins lymphoma (1 paper, 2021). A heterogeneous group of malignant lymphoid neoplasms of B-cell origin characterized histologically by the presence of Hodgkin and Reed-Sternberg (HRS) cells in the vast majority of cases. "Hyaluronan-binding protein 4 (HABP4, also named Ki-1/57), an intracellular cross-reactant of the monoclonal antibody Ki-1, has been the first protein used to specifically detect malignant cells in Hodgkin’s lymphoma." (PMID 33775245, 2021). "HABP4, a nuclear and cytoplasmic regulatory protein first identified in malignant cells from Hodgkin’s lymphoma, had been found to participate in different physiological functions, including cell proliferation, tumorigenesis, RNA transcription and splicing, and telomere maintenance." (PMID 33775245, 2021).
liver cancer (1 paper, 2020). An epithelial or non-epithelial malignant neoplasm that arises from the liver. "Also in 50% of the metastasis of liver cancer had diminished or absent expression of the HABP4 protein." (PMID 33245729, 2020).
renal carcinoma (1 paper, 2024). A carcinoma arising from the epithelium of the renal parenchyma or the renal pelvis. "In contrast, the downregulation of let7i observed in our study could also alter the angiogenic function of EPCs by suppressing their migratory activity; let7i enhances cell migration and proliferation by targeting HABP4 in renal carcinoma cells." (PMID 39767576, 2024).
tumor (4 papers, 2020 to 2023). "After gene knockout, tumor volume increased, indicating that HABP4 is expected to become a new tumor suppressant protein." (PMID 37020597, 2023). "Our results provide evidence that let-7i-5p functions as a tumor promoter in ccRCC and facilitates cell proliferation, migration and invasion by targeting HABP4." (PMID 33775245, 2021). "The present study has been the first to report that HABP4, a target gene of let-7i-5p, functioned as a tumor suppressor gene in ccRCC." (PMID 33775245, 2021). "Meanwhile, the present study has been the first to confirm that HABP4, a target gene of let-7i-5p, could be considered a tumor suppressor gene in ccRCC." (PMID 33775245, 2021). "On the other hand, 30% of the tumor tissues present low or no HABP4 expression (p < 0.0001)." (PMID 33245729, 2020).
cancer (3 papers, 2006 to 2021). A tumor composed of atypical neoplastic, often pleomorphic cells that invade other tissues. "43% of the mutations found for HABP4 in cancer, are found in samples from patients with cancers in the digestive tract: intestine (13%), stomach (6%), esophagus (4%), upper aerodigestive tract (3%), pancreas (4%) and liver (13%)." (PMID 33245729, 2020). "Studies have shown that HABP4 overexpression resulted in reduced cancer cell proliferation, mainly because of a G1 phase arrest, and that HABP4 could influence the splicing pattern of the E1A pre-mRNA by binding with the endogenous splicing proteins hnRNPQ and SFRS9." (PMID 33775245, 2021).
HABP4 also shares sentences with these, for which no sentence is quoted: adenocarcinoma (1 paper); atherosclerosis (1); clear cell renal cell carcinoma (1); colitis (1); colorectal cancer (1); fragile X syndrome (1); Gorlin syndrome (1); leukemia (1); lung carcinoma (1); mental retardation (1); mucinous adenocarcinoma (1); ovarian carcinoma (1); papillary adenocarcinoma (1); Parkinson’s (1); schizophrenia (1).